RNU6-1225P (RNA, U6 small nuclear 1225, pseudogene)
Gene: Small nuclear RNA gene on chromosome X (68,102,068 to 68,102,132, reverse strand). Ensembl gene ENSG00000252145.
Homologues: Orthologues: chimpanzee U6 (98% identical), macaque U6 (92% identical), dog U6 (91% identical), mouse Gm55877 (86% identical), guinea pig U6 (85% identical). Paralogues in human: RNU6-20P (97% identical), RNU6-16P (95% identical), RNU6-1 (94% identical), RNU6-1145P (94% identical), RNU6-11P (94% identical), RNU6-1316P (94% identical), RNU6-1323P (94% identical), RNU6-144P (94% identical), RNU6-15P (94% identical), RNU6-2 (94% identical), RNU6-25P (94% identical), RNU6-333P (94% identical), and 1284 more.